CD4 (CD4 molecule)
Diseases named in the same sentence as CD4 in open-access papers (continued):
Sharing a sentence is not in itself a finding about the gene and the disease.
autoimmune disease (continued). "Later on, NKG2D+ CD4+ T cells have been associated with several other autoimmune diseases, such as Crohn’s disease, Wegener granulomatosis, type 2 diabetes, multiple sclerosis, and systemic lupus erythematosus (SLE)." (PMID 29740438, 2018). "Data of animal experiments indicate that the number of naturally occurring CD4+CD25+ Tregs is associated with autoimmune diseases as well as atherosclerosis." (PMID 29976209, 2018). "The transcription factor aryl hydrocarbon receptor (AHR) regulates the generation of Th17 cells, CD4 T cells linked the development of autoimmune diseases." (PMID 29884199, 2018). "Basophil-deficient mice show a reduced phenotype of the autoimmune disease through diminished incidence and lower infiltration of CD4 T cells." (PMID 28134325, 2017). "The role of the PD-1 pathway in maintaining immune tolerance at the level of DC-T cell interactions has been well established, and persistent activation of self-reactive CD4+ T cells is a pathogenic hallmark of autoimmune diseases such as SLE." (PMID 28274252, 2017). "Since immunity and susceptibility to autoimmune disease is well-known to be influenced by age and gender, we analyzed the IL-10 response in CD4+ T cells from both male and female mice within an age range from 7 to 18 weeks." (PMID 28742882, 2017). "Here we show cell type-specific regulation of transcript levels of genes associated with several autoimmune diseases in CD4+ and CD8+ T cells including a trans-acting regulatory locus at chr12q13.2 containing the rs1131017 SNP in the RPS26 gene." (PMID 28248954, 2017). "Breg have shown to regulate various immune responses including regulation of generation of CD4+ Treg; deficiency of Breg results in experimental autoimmune diseases, and more recently, Breg were shown to regulate the generation of peripheral CD4+ Treg cells." (PMID 28928736, 2017). "The lack of a functional Foxp3 transcription factor and regulatory T (Treg) cells causes lethal, CD4+ T cell-driven autoimmune diseases in scurfy (SF) mice and humans." (PMID 29270168, 2017). "Depletion of CD4+ cells in MCMV-infected mice abrogated susceptibility to MOG35–55-induced disease indicating autoimmune disease." (PMID 28289417, 2017). "Autoimmune disease-associated variants are preferentially found in regulatory regions in immune cells, particularly CD4+ T cells." (PMID 28870212, 2017). "Circulating follicular helper T (Tfh) cells are a heterogeneous population of CD4+ helper T cells that promotes pathogenic immune responses in autoimmune diseases." (PMID 27769184, 2016). "IL-22 is a member of IL-10 cytokine family that was discovered to be mainly produced by CD4+ T cells and associated with several autoimmune diseases such as inflammatory bowel diseases (IBD), psoriasis and systemic lupus erythematosus (SLE)." (PMID 27467597, 2016). "Since functional defects in Treg cells can cause autoimmune disease, the immune-regulatory activity of Treg cells was evaluated by analyzing the proliferation of co-incubated Teff (CD4+CD25− T) cells from WT NOD mice." (PMID 27880731, 2016). "CD4+ T cells play a multiplicity of roles in cellular immunity and T cell dependent antibody responses, and both CD4+ effector T cells and follicular CD4+ helper T cells have been implicated in autoimmune diseases." (PMID 28066418, 2016). "Specifically, T helper 17 cells (Th17), which are a distinct lineage of CD4+ T-cells that produce characteristic cytokines like IL-17 and IL-22, have been implicated in a variety of autoimmune diseases and irAEs, particularly colitis." (PMID 27660709, 2016). "EAE is a T cell-mediated autoimmune disease characterized by perivascular CD4+ T cell and mononuclear cell infiltration, causing demyelination areas in the central nervous system, leading to progressive hind-limb paralysis." (PMID 27478856, 2016).
autoimmune disease (continued). "Classical MHC class II (MHCII) proteins present peptides for CD4+ T-cell surveillance and are by far the most prominent risk factor for a number of autoimmune disorders." (PMID 27534821, 2016). "Th17, a newly defined CD4+ Th subset, has been implicated in the pathogenesis of many diseases, particularly autoimmune disorders." (PMID 25621490, 2015). "The absence of functional Tregs is associated with the development of a multiorgan autoimmune disease due to activation of autoreactive CD4+ T cells and additional B cell-mediated disease." (PMID 25890083, 2015). "Th17 cells, CD4+ T cells that secrete IL-17, are pathogenic in autoimmune diseases, and their differentiation and expansion are driven by the cytokines IL-6 and TGF-β." (PMID 26071315, 2015). "On the other hand, AD is an autoimmune disorder associated with the imbalance of CD4+T cells during immune responses such as Th1/Th2 bias." (PMID 26244559, 2015). "Specifically, they displayed loss of CD4+FoxP3+ Treg cell suppressive function, hyperactivation of effector T cells, lymphocyte infiltration of multiple target organs, and fatal autoimmune disease." (PMID 25852682, 2015). "Several studies have demonstrated increased percentages of FOXP3+ CD4+ T cells in the periphery and reduced organ-specific autoimmune disease susceptibility, including T1D in the NOD model." (PMID 26438525, 2015). "Collectively, our data suggest that early treatment with anti-VLA-4 mAb can provide neuroprotection against progressive CNS autoimmune disease by preventing the accumulation of pathogenic GM-CSF-producing CD11b+CD4+ T cells in the CNS." (PMID 24896098, 2014). "Conversely, adoptive transfer of wild-type CD4+ T cells was able to partially rescue LAG-3-deficient mice from the autoimmune disease." (PMID 25122007, 2014). "To elucidate mechanisms of autoimmune disease alleles, we investigated molecular phenotypes in CD4+ effector memory T cells potentially affected by these variants." (PMID 24968232, 2014). "Another characteristic associated with autoimmune diseases is premature aging in CD4+ T/T cell compartment (hereafter referred to as premature CD4+ T/T cell aging)." (PMID 24586733, 2014). "CD4 T regulatory cells (Tregs) are crucial for the maintenance of self-tolerance and are deficient in many common autoimmune diseases such as type 1 diabetes (T1D)." (PMID 24898091, 2014). "Dysfunction of nTreg cells means loss of balance between CD4+ T helper cells subsets (Th1, Th2, Th17, Treg) which is supposed to participate in other autoimmune diseases, such as MG and T1D." (PMID 24672784, 2014). "It would be informative to determine the phenotype of mice with autophagy deficiency in DCs, in autoimmune disease models of MS, a predominantly CD4 T cell mediated disease, or rheumatoid arthritis." (PMID 23596443, 2013). "CD4+ T helper (Th) cells differentiate into distinct effector subsets that are critical for host defense, but are also implicated in the pathogenesis of autoimmune disorders." (PMID 23555662, 2013). "We have confirmed that the observation of significant overlap between VDR binding and genomic regions implicated in autoimmune diseases in LCLs is also seen in primary CD4+ cells." (PMID 23849224, 2013). "IL-17-producing CD4+ T helper 17 (Th17) cells are pathogenic in a range of human autoimmune diseases and corresponding animal models." (PMID 23437182, 2013). "Th17 cells, a CD4 T helper subset characterized by the production of IL-17A, IL-17F, IL-21, and IL-22 cytokines, are implicated in the pathogenesis of many autoimmune diseases." (PMID 23505568, 2013). "SLE is an autoimmune disease characterized by the loss of immune tolerance, resulting in activation and expansion of autoreactive CD4+ T-helper cells." (PMID 23975170, 2013). "Historically, MS has been considered as an autoimmune disease mediated mainly by CD4 T cells, and associated, at least in part, with alleles, MHC-II." (PMID 24174971, 2013).
autoimmune disease (continued). "In fact, SNPs located within the extended murine IL2 promoter, which associate with autoimmune disease, were found to alter the gene transcription in CD4+ T cells and diminished interleukin-2 synthesis was reported for a susceptible haplotype in NOD mice." (PMID 24154763, 2013). "In another model system, adoptive transfer of thymocytes or peripheral T cells depleted of CD4+CD25+ TReg cells causes autoimmune diseases in mice, which provides further evidences of thymic origin of TReg cells and their peripheral existence." (PMID 22481922, 2012). "Our finding that CD56bright NK cells readily degranulate and kill activated CD4+ T cells has interesting therapeutic implications, as NK cells with a CD56bright phenotype have been implicated in numerous autoimmune diseases." (PMID 22384114, 2012). "On the other hand, it is well known that impaired Treg function is also associated with pathogenesis of autoimmune disease, and that CD4+/CD25+/Foxp3+ cells represent one of the major Treg cells involved in susceptibility/resistance to autoimmunity." (PMID 22028728, 2012). "CD4+ IFN-γ-producing Th1 cells have long been associated with the pathogenesis of many organ-specific autoimmune diseases." (PMID 23049532, 2012). "Subsequently, the depletion of CD4+CD25+ Tregs leads to spontaneous development of various autoimmune diseases in genetically susceptible animals as well." (PMID 21647403, 2011). "It has also been shown that STAT1-deficient mice are highly susceptible to autoimmune diseases resulting from a reduced number as well as a functional impairment of CD4+CD25+ nTreg, suggesting a role of IFNs on regulatory T cells." (PMID 21647403, 2011). "Th17 cells, which are a subset of effector CD4+ T cells specialized in the production of IL-17 and IL-22 and in recruitment and activation of neutrophils, have been implicated in autoimmune diseases, including multiple sclerosis, lupus and diabetes." (PMID 21494636, 2011). "Specific deficiency of Ctla4-/- in natural Foxp3+CD4+ regulatory T cells results in spontaneous autoimmune disease." (PMID 19951419, 2009). "Thymectomized neonatal mice are deficient in CD4+CD25high regulatory T cells and develop multi-organ autoimmune disease, which can be overcome by the adoptive transfer of CD25+ thymocytes from normal mice." (PMID 19046457, 2008). "Children with thymic hypoplasia as a result of the 22.q2 deletion syndrome display impaired CD4+CD25high regulatory T cell generation and have an increased risk of developing an autoimmune disorder." (PMID 19046457, 2008). "Th17 cells are a unique subset of CD4+ TH cells and recent studies suggest that Th17 cells have an important pathogenic role in T cell mediated autoimmune disease and tissue inflammation." (PMID 18382691, 2008). "In humans, decreased frequency of peripheral blood CD4+CD25high Treg have been linked to different types of autoimmune diseases like rheumatoid arthritis, type-1 diabetes, multiple sclerosis and systemic lupus erythematosus." (PMID 17712427, 2007). "Among the autoimmune disorders, CD risk variants were particularly highly enriched within the active PIRs of both ILC3s and CD4+ T cells (~2.3-fold enrichment in both cell types, p-value = 1.41 × 10−8 in ILC3s and p-value = 2.41 × 10−10 in CD4+ T cells)." (PMID 41573945, 2026). "TYK2:p.Pro1104Ala variant confers protection from several autoimmune disorders but predisposes to infection and we show that the mechanism of its action includes an increase of the levels of lymphocytes in all compartments (CD4+, CD8+ and B), but these cells are mainly naive." (PMID 39835539, 2025). "For example, cytokine co-expressing T cells such as IFN-γ+ IL-17+ CD4+ T cells, which are increasingly recognized as pathogenic in RA and other autoimmune diseases, cannot be reliably distinguished from conventional Th1 or Th17 cells using surface markers alone." (PMID 40777029, 2025).
autoimmune disease (continued). "Genetic control of CD4 frequency has been described and linked to autoimmune disease." (PMID 40525756, 2025). "In addition, other pathways such as Wnt and MAPK, which are implicated in autoimmune diseases, also exhibit increased methylation in aged CD4+ T cells." (PMID 40410784, 2025). "Among these, CD4(+) T cells are recognized as pivotal contributors to adaptive immunity, playing a crucial role not only in eliminating pathogens, but also in regulating autoimmune diseases and targeting pathogenic cells such as cancer cells." (PMID 39851522, 2025). "Tfh cells, a subset of CD4+ T cells, have been implicated in autoimmune diseases, including SSc." (PMID 38280030, 2024). "In autoimmune diseases, the immune system lacks the ability to distinguish “self” from “non-self” proteins, and select antigens can initiate a proinflammatory immune response that expands CD4 T cells that cause autoimmune pathology." (PMID 39559361, 2024). "Although Tfh cells are the main CD4+ T-cell subpopulation involved in the generation of autoantibodies, recent research has focused on a novel subpopulation that appears to be more closely associated with the pathogenesis of autoimmune diseases." (PMID 39062968, 2024). "CD4+ CD28- T cells are associated with autoimmune diseases like rheumatic arthritis." (PMID 39399489, 2024). "Experimental and human studies have reported a correlation between relatively high total serum bilirubin levels and a reduced risk of CD4+ T cell‐related autoimmune disorders, such as multiple sclerosis, systemic lupus erythematosus, rheumatoid arthritis, and inflammatory bowel disease." (PMID 38313187, 2024). "Dysregulation of CD4+ T cell differentiation is linked to autoimmune diseases." (PMID 37851814, 2023). "This reduction in CD4 + T cells, particularly Treg cells, by Sitagliptin might increase the risk of infection or autoimmune diseases, including autoimmune arthritis, in type 2 diabetes patients." (PMID 38065905, 2023). "Therefore, it appears that iASPP−/− mice with EAE have a less potent autoimmune antigen-specific T cell response, suggesting that iASPP predisposes mice to more severe CNS autoimmune disease by fostering CD4+ T cell-mediated neuroinflammation." (PMID 36746936, 2023). "Application of mimotopes in the treatment of autoimmune diseases will depend to a large extent upon their ability to suppress immunoreactivity, for instance by stimulating regulatory anti-inflammatory CD4+ T cells, or by directly inhibiting pathogenic cytotoxic CD8+ T cells." (PMID 37409132, 2023). "In summary, our data clarified that DNA accumulation in CD4+ T cells triggered glycolysis, and then caused autoimmune diseases, which may be a new explanation for harboring DNA metabolism leading to autoimmune diseases." (PMID 39872301, 2023). "Moreover, the challenge in using single chain variable fragment CAR T cell therapy for autoimmune diseases lies in identifying a specific cellular target for the pathogenic CD4+ T cells." (PMID 37427200, 2023). "Autoimmune diseases are also associated with Th2 CD4 T-cells, which are induced by IL-4." (PMID 36830745, 2023). "Moreover, epigenetic markers can also affect the expression level of a gene, leading to abnormal CD4+ T-cell function, which in turn increases the risk of autoimmune disease." (PMID 36189300, 2022). "Among them, Th17 cells are identified as effective CD4+ T cells that play an essential role in autoimmune diseases and inflammation which may be associated with anti-tumor responses." (PMID 35248028, 2022). "Besides the expansion of pathogenic Th17 cells, autoimmune diseases are classically associated with impaired production of the anti-inflammatory cytokine IL-10 by regulatory CD4+ T cells." (PMID 35109870, 2022).
autoimmune disease (continued). "In this study, we investigated the immunomodulatory effect of Tpp53 using imiquimod (IMQ)-induced psoriasis-like dermatitis model, which is a mouse model of autoimmune disease with the pathogenic interleukin 17 (IL-17) producing CD4+ T cells (Th17) via IL-23/IL17 axis." (PMID 36620087, 2022). "Furthermore, several studies determined that TS patients with an increased risk of autoimmune disorders exhibit a lower percentage of CD4+ cells and a lower CD4+:CD8+ ratio." (PMID 34434978, 2021). "However, UMCD6 does have important effects on activation and differentiation of CD4+ cells that underlie the beneficial results of its use in animal models of human autoimmune diseases." (PMID 33497367, 2021). "Previous studies showed that TRB junction regions in polyclonal memory CD4+ T cell subsets were shorter in T1D than HC donors, which may increase the potential for self-recognition and heighten risk of autoimmune disease." (PMID 34806648, 2021). "However, contradictory reports have indicated that in some autoimmune diseases such as systemic lupus erythematosus, these CD4+CD25– FoxP3+CD127low/– dysfunctional Treg are associated with disease activity." (PMID 34502490, 2021). "T regulatory cells (Tregs) are also decreased in AA and their ability to suppress autoreactive clones is reduced, while Th17 cells, associated with autoimmune disorders, are frequently increased, are correlated to disease severity, and are inversely related to the number of CD4+CD25highFoxP3+ Tregs." (PMID 33445786, 2021). "As a result, we provide a rich resource of integrated chromatin accessibility (ATAC-seq) and transcriptome (RNA-seq) data from these primary human CD4 T cell subsets and we show that the identified signatures are associated with human autoimmune diseases, especially multiple sclerosis." (PMID 34285924, 2021). "Considering that T1D is a complex autoimmune disease characterised by insulitis, the chronic inflammation of the pancreatic islets of Langerhans caused by autoreactive CD4+ and CD8+ T cells, pathways related to immune response are expected to be enriched along with the T1D pathway." (PMID 32518234, 2020). "Abnormal CD4+ T-cell proliferation has been implicated in the development of various diseases including peripheral T-cell proliferative diseases/lymphomas, inflammatory/infection diseases, graft-versus-host disease and autoimmune diseases." (PMID 33117376, 2020). "In summary, our findings suggested that abnormalities of the CD4+T cell subset related to the nature of the autoimmune disease might make the patient more susceptible to infectious pathogens, regardless of treatment with immunosuppressive agents." (PMID 30994732, 2019). "Based on these observations, we hypothesized that let-7 miRNAs inhibit the differentiation of CD4+ T cells and may therefore compromise the generation of pathogenic Th17 cells and suppress the development of autoimmune disorders." (PMID 32010153, 2019). "Different data indicate the relevant role of these CD4+Foxp3+ Treg cells in the pathogenesis of autoimmune diseases, including the congenital deficiency of Foxp3, which results in the IPEX syndrome (immune dysregulation, autoimmune polyendocrinopathy, and inflammatory enteropathy)." (PMID 30116758, 2018). "Moreover, PSMα3-induced tDCs from healthy donors even enhanced differentiation of CD4+ T cells from patients with Th17-associated autoimmune diseases to Tregs." (PMID 30555457, 2018). "In this review, we describe how WTD promotes intestinal and extra-intestinal inflammation and alters mucosal immunity acting on CD4+ T cells in a microbiota-dependent or –independent fashion, ultimately leading to higher susceptibility to infectious and autoimmune diseases." (PMID 30697217, 2018).